SOX10 (SRY-box transcription factor 10)
Diseases named in the same sentence as SOX10 in open-access papers (continued):
Sharing a sentence is not in itself a finding about the gene and the disease.
melanoma (continued). "Nevertheless, the regulation of DEPDC1B by SOX10 is further supported by their co‐expression in most biopsies from different stages of melanoma, strongly suggesting that SOX10 is one of the upstream factors contributing to the abnormal upregulation of DEPDC1B expression in melanoma." (PMID 35088579, 2022). "High SOX10 expression positively regulates melanoma cell proliferation, tumor growth, and invasion." (PMID 35296667, 2022). "For RT‐PCR analyses, we chose melanophore marker genes pmel and mitf, neural crest markers sox10 and slug that can be reactivated in invasive melanomas, melanoma‐enriched genes bcl2 and axl, and cdh1 (E‐cadherin gene), of which expression was decreased in invasive melanomas." (PMID 35981147, 2022). "Furthermore, we predicted the binding of different transcription factors on the SMARCA4 promoter and unveiled the modulated expression of SMARCA4 by SOX10 in melanoma." (PMID 36317703, 2022). "Altogether, our findings reveal a SOX10‐DEPDC1B‐SCUBE3 regulatory axis that promotes melanoma angiogenesis and facilitates its metastatic progression, suggesting the possibility of targeting secreted SCUBE3 as a therapeutic strategy against metastatic melanoma." (PMID 35088579, 2022). "SOX10, a neural crest lineage transcription factor, is heterogeneously expressed in melanomas." (PMID 35296667, 2022). "SOX9 and SOX10 show antagonistic functions in the regulation of melanoma phenotype." (PMID 35406721, 2022). "To examine whether DEPDC1B functions downstream of SOX10 to regulate melanoma growth and metastasis, we performed an epistasis analysis." (PMID 35088579, 2022). "The authors’ findings suggest that, in the diagnosis of malignant melanoma, SOX10 and KBA.62 may be useful, particularly in the diagnosis of amelanotic malignant melanoma." (PMID 35954389, 2022). "Similarly, a possible direct involvement of SOX10 in regulating melanoma metabolic rewiring will also demand deeper attention." (PMID 35912100, 2022). "Interacts with MITF and SOX10 in melanocytes and melanoma cells." (PMID 35323214, 2022). "As expected, the major cellular population within these PDX tumors was SOX10+ melanoma cells." (PMID 34092233, 2021). "Although the reduction of Brn2 in Braf-Pten-Brn2 primary melanoma is not sufficient to re-induce Mitf mRNA and pigmentation in all cells of these primary melanomas, the Braf-Pten melanoma cells that formed LN metastases were pigmented and re-expressed Sox10, a key transcription activator of Mitf." (PMID 34140478, 2021). "Indeed, human melanomas immunostain positive for SOX10 in most cases, even more often than the key melanocyte lineage regulator MITF38–40." (PMID 34099848, 2021). "A possible reason is that SOX9/SOX10 signaling may be disrupted in highly malignant melanoma cells; therefore, it likely plays a more important role in carcinogenesis compared with that in malignancy." (PMID 34526609, 2021). "Hypoxia led to the elevated expression of mesenchymal markers (Snail1, N-cadherin (neuronal cadherin), α-SMA (α-smooth muscle actin), SOX10 (SRY-box transcription factor 10)) with simultaneous reduction in E-cadherin (epithelial cadherin) level in melanoma cells." (PMID 33918883, 2021). "Furthermore, mRNA levels for SOX10, a marker for melanoma sentinel lymph node metastasis, displayed higher levels in hPL supplemented culture." (PMID 34768746, 2021). "Moreover, it has been observed that CD271 and SOX10, two factors associated with NCSC regulatory networks, are highly expressed in human melanoma and their expression is correlated with a high metastatic potential and a worse patient prognosis." (PMID 34830940, 2021). "Interestingly, PITX1 binds to the SOX9 promoter region as a positive regulatory transcription factor; PITX1 mRNA expression levels were positively correlated with SOX9 expression, and negatively correlated with SOX10 expression in melanoma tissues." (PMID 34526609, 2021).
melanoma (continued). "However, SOX10 can also promote invasion by upregulating its direct target genes melanoma inhibitory activity (MIA) and peripheral myelin protein 2 (PMP2)." (PMID 34071193, 2021). "Further study involving a detailed analysis of the regulation of miR-19b and SOX10 transcription may contribute greatly to the discovery of a novel melanoma inhibition pathway." (PMID 34526609, 2021). "SOX10 expression was positively correlated with the conventional pan-melanoma cocktail." (PMID 33801642, 2021). "Survival-Associated Mitochondrial Melanoma Specific Oncogenic Non-Coding RNA (SAMMSON) is a melanoma-specific lncRNA and its expression is positively regulated by SOX10, a transcription factor responsible for the development of neural and pigment cells, that derive from the neural crest." (PMID 34638331, 2021). "We assessed expression of ROPN1B, NY-ESO-1 (single protein from CTAG1A or CTAG1B genes), MLANA and SOX10 (used here as a melanoma tumour marker) at the protein level by multispectral immunohistochemistry on melanoma tissue microarrays (TMAs) comprising two or three cores from 61 patient tumours." (PMID 33918976, 2021). "The role of a neural crest developmental transcriptional program, which critically involves Sox10 upregulation, is a key conserved aspect of melanoma initiation in both humans and zebrafish, yet transcriptional regulation of sox10 expression is incompletely understood." (PMID 34099848, 2021). "Notably, they identified enrichment of H3K27ac marks in super-enhancers at the sox10 locus, a major regulator of neural crest formation and melanomagenesis, suggesting that epigenetic regulation of SOX10 is an important step in melanoma initiation." (PMID 34575678, 2021). "Notably, we observe a significant induction of CD40+SOX10+ melanoma cells in the tumors of melanoma patients post BRAF inhibitor treatment by multiplex IHC analysis." (PMID 34092233, 2021). "Past work demonstrated that modulation of sox10 expression in melanocytes, which normally express sox10 at low levels, affects melanoma onset rates, illustrating that regulation of sox10 plays a key role during melanoma initiation." (PMID 34099848, 2021). "A large number of reports regarding very high sensitivity of the SOX10 protein in melanoma may indicate that it is a good marker in diagnosing this neoplasm." (PMID 33503841, 2021). "Yang and colleagues found that knocking down only YTHDF2 significantly increased the mRNA stability of PD-1 (PDCD1), CXCR4, and SOX10; in conjunction, the proliferative and migratory capacities of the melanoma cells were increased (in vitro) as was tumor growth (in vivo)." (PMID 34105069, 2021). "SOX10, a melanoma specific marker, was stained simultaneously to distinguish melanoma cells." (PMID 33478111, 2021). "ATAC-Seq on melanoma tumor cells showed consistent regions of open chromatin and identified 11 such regions of open chromatin around and within the sox10 locus, including a putative sox10 minimal promoter encompassing exon 1 of sox10." (PMID 34099848, 2021). "Interestingly, SOX10 is highly expressed in melanoma cell lines when compared to other cancer cells." (PMID 33507915, 2021). "Additionally, mouse Sox10 haploinsufficiency fully prevents NrasQ61K-driven formation of melanoma development in vivo, which shows that SOX10 plays a crucial role in melanomagenesis." (PMID 34526609, 2021). "In this study, we functionally screen putative enhancer elements, identified as accessible or “open” regions of chromatin using ATAC-Seq on zebrafish melanomas, near the sox10 gene for transcriptional activating, or enhancer, activity in embryonic neural crest as well as in melanoma tumors." (PMID 34099848, 2021). "In addition to its role in melanoma progression, the authors showed that UBE2N positively regulated and maintained the MEK/FRA1 (Fos-Related Antigen 1)/SOX10 (SRY-related HMG box-containing factor 10) signaling cascade that plays a key role in melanomas." (PMID 33800394, 2021).
melanoma (continued). "Importantly, SOX10 is not only a melanoma marker but is functionally important for melanoma cells survival." (PMID 32238882, 2020). "SOX10 knockout downregulates the expression, activity, and migration of melanoma cells." (PMID 33344444, 2020). "In particular, at early stages of melanoma development, Rab7a is upregulated and sustains melanoma cell proliferation controlled by the lineage-specific transcription factor SOX10 and the oncogenic transcription factor MYC, which is activated at early stages of melanoma development." (PMID 33195279, 2020). "Additionally, they discovered that the overexpression of SOX10 in melanocytes accelerates melanoma formation by activating NC progenitor genes and super enhancers." (PMID 33344444, 2020). "To test the first hypothesis, we characterized changes in SOX10 mRNA levels in the melanoma cultures upon CHIR99021 treatment." (PMID 32238882, 2020). "Importantly, we observed a significant decrease in H3K4me3 enrichment at the melanoma-associated genes, CD271, AXL, SOX10, and MITF." (PMID 32620791, 2020). "First, we performed immunohistochemistry for SOX10 in a set of human melanoma samples." (PMID 32238882, 2020). "Recently, it has been suggested that SOX10 is highly relevant to melanoma development." (PMID 33344444, 2020). "In melanoma, SOX10 is essential for the maintenance of proliferation." (PMID 32899370, 2020). "Scrapings from a pathological hip fracture 3 months later revealed focal synaptophysin immunoreactivity and widespread melanoma antigen, human melanoma black 45, and SOX10 positivity, which are indicative of metastatic malignant melanoma with focal neuroendocrine differentiation." (PMID 32234068, 2020). "Moreover, it was observed that DIRC3 depletion induces an increased SOX10 (SRY-box transcription factor 10) repression of IGFBP5 in melanoma cell cultures, corroborating the tumor suppressor role of DIRC3." (PMID 33218058, 2020). "Stable SOX10 knockout reduces the level of E2F transcription factor 1 (E2F1) in melanoma cells." (PMID 33344444, 2020). "Strikingly, even the combination of a BRAF and a MEK inhibitor, which is the new standard of care treatment in patients with BRAFV600E-mutated melanoma, did not alter SOX10 expressions levels." (PMID 32238882, 2020). "However, we have now identified a new mechanism to successfully suppress SOX10 pharmacologically in malignant melanoma." (PMID 32238882, 2020). "Our rescue and the RNA-sequencing experiments on the other hand demonstrate that the impairment of melanoma cell survival provoked by SOX10 suppression upon GSK3α/β inhibition is dependent on β-catenin, suggesting a direct involvement of canonical WNT/β-catenin signaling." (PMID 32238882, 2020). "These authors discovered that SOX10, as the substrate of Fbxw7α-binding E3 ubiquitin ligase, could promote the migration of melanoma cells mediated by Fbxw7α." (PMID 33344444, 2020). "Low SOX10 expressing melanoma cells have been shown to adapt to BRAF inhibition." (PMID 31118886, 2019). "These comparisons identified 90 pigmentation/melanoma GWAS loci that overlap with regions of H3K27ac acetylation and/or SOX10 ChIP-Seq binding, thus highlighting the variants located within these regions as high priority candidates for future studies of the function of these distal enhancers." (PMID 31399133, 2019). "Although both SOX9 and SOX10 exhibit differential expression patterns in melanomas, whether they share the same or distinct transcriptional targets in mediating the oncogenic events is not known." (PMID 30642390, 2019). "Although we can’t rule out the possibility that DIRC3 also regulates IGFBP5 independently of SOX10, our results are consistent with a model in which DIRC3 acts locally to block SOX10 chromatin binding at melanoma regulatory elements and activate IGFBP5 expression." (PMID 31881017, 2019).
melanoma (continued). "Thus, we anticipated that SOX10 or high level of SOX9 regulates NEDD9 expression to promote melanoma migration through alteration of focal adhesion dynamics and RHO signaling activity." (PMID 30642390, 2019). "Furthermore, SOX10 is required for melanoma initiation, survival and progression, and cellular levels of SOX10 affect acquired resistance to melanoma inhibitor drugs." (PMID 31399133, 2019). "Furthermore, we found that overexpression of PD-1 (PDCD1), CXCR4, or SOX10 inhibited IFNγ-induced cell death in FTO-knockdown melanoma cells." (PMID 31239444, 2019). "We revealed that further increased SOX9 dosage with comparable expression levels to a range of high SOX9 mRNA detected in malignant melanoma specimens could restore the metastatic properties in SOX10 knockdown cells, partly through induction of NEDD9 activity." (PMID 30642390, 2019). "These prompted us to examine whether SOX10 regulates NEDD9 expression in two metastatic melanoma cell lines (A375M and WM266–4) harboring mutated BRAF, which express high levels of SOX10 and NEDD9 expression." (PMID 30642390, 2019). "Based on the demonstration that either SOX10 phosphorylation or SOX10 sumoylation play an important role in its expression and in the activation of its downstream targets in melanoma, it would be interesting to investigate the role of SOX10 post-translational modifications in drug resistance." (PMID 31118886, 2019). "Thus, the levels of the upregulated SOX9 expression in SOX10 KD melanoma cell lines are similar to the low mRNA levels of SOX9 detected in cutaneous melanoma specimens." (PMID 30642390, 2019). "We observed a significant reduction of NEDD9 transcripts in SOX10 KD compared to control, suggesting that NEDD9 expression could be regulated by SOX10 in melanoma cells." (PMID 30642390, 2019). "SOX10 has been described as an additional marker for melanoma." (PMID 30205833, 2018). "At the initial stage of drug treatment, SOX10 may provide rapid protection on melanoma cells by upregulating pro-survival factors such as FOXD3, MITF, and SAMMSON and therefore is important for the survival of melanoma cells." (PMID 29295999, 2018). "Our findings not only delineate a signaling network that governs the FOXD3-mediated adaptive resistance to RAF inhibitors in mutant BRAF melanoma but also demonstrate an intricate regulatory switch of SOX10 transcription activity that involves interplay between phosphorylation and sumoylation." (PMID 29295999, 2018). "Thus maintenance of SOX10 expression is important in tumor initiation, maintenance, and progression to advanced stages of melanoma." (PMID 29315345, 2018). "Finally, depletion of SOX10 sensitizes mutant BRAF melanoma cells to RAF inhibitors in vitro and in vivo." (PMID 29295999, 2018). "This could provide important insight into the regulation of SOX10 protein levels in melanoma cells, and contribute to our understanding of pathways involved in tumor-acquired resistance." (PMID 29315345, 2018). "We then investigated whether SOX10 is a mediator of the ERK-dependent regulation of FOXD3 in mutant BRAF melanoma cells." (PMID 29295999, 2018). "Thus, in addition to the NC1 and NC2 enhancer-mediated regulation of FOXD3, the SOX10/FOXD3 axis discovered in mutant BRAF melanoma cells is likely a new component of the complex regulatory network that controls the development of neural crest." (PMID 29295999, 2018). "This suggests SOX10 can regulate EGFR levels in melanoma, and that reducing SOX10 protein may play an important role in acquired resistance." (PMID 29315345, 2018). "This study provides a functional assessment of phosphorylation that occurs on SOX10 protein in melanoma cells, highlighting specific residues that may modulate SOX10 protein levels." (PMID 29315345, 2018).
melanoma (continued). "Indeed, we identify SOX10 as a novel regulator of FOXD3 in human mutant BRAF melanoma that binds to a conserved regulatory element located 270 bp upstream from the transcription starting site and activates FOXD3 transcription." (PMID 29295999, 2018). "Thus, our work discovers a novel phosphorylation-dependent regulatory mechanism of SOX10 transcription activity and completes an ERK1/2/SOX10/FOXD3/ERBB3 axis that mediates adaptive resistance to RAF inhibitors in mutant BRAF melanoma cells." (PMID 29295999, 2018). "Therefore, SOX10 depletion can sensitize mutant BRAF melanoma cells to Vemurafenib in vitro and in vivo." (PMID 29295999, 2018). "Another mechanism through which SOX10 mediates melanoma development—in cooperation with MYC—is related to the induction of a lysosomal program of gene expression: melanoma cells exploit the development of lysosomal degradation pathways to accelerate tumor growth." (PMID 29156643, 2017). "Interestingly, the SOX10 transcription factor which is required for melanocyte development is prominently expressed in giant congenital naevi and melanoma, while SOX10 gene silencing effectively blocks human melanomagenesis in vivo." (PMID 28158294, 2017). "Our findings may also impact the understanding and treatment of melanoma, as the Sox10 target MITF is a lineage oncogene in this neural crest-derived cancer." (PMID 28832322, 2017). "Melanoma is an aggressive, NC-derived tumor, initiation of which involves a NC-like state, i.e., the reactivation of early, neurula-stage NC-specific genes such as sox10 in adults." (PMID 29049289, 2017). "Importantly, SOX10 silencing in human melanoma cells suppresses neural crest stem cell properties, counteracts proliferation and cell survival, and completely inhibits tumor formation in vivo." (PMID 29156643, 2017). "For these SOX10 positive patients, showing no sign of recurrent disease, a possible explanation for the SOX10 release could be functional immune surveillance and lysis of melanoma cells by immune mechanisms." (PMID 27110718, 2016). "Interestingly, also SOX5 (p = 0.0008) and SOX10 (p = 3E-6) showed a significantly higher expression in melanoma samples compared to all other cells." (PMID 26927636, 2016). "Additionally, we found that SOX5 knockdown led to MITF up-regulation in melanoma cells, while double knockdown with SOX10 showed a rescue effect; both effects were validated by reporter assays." (PMID 26927636, 2016). "Shakova and coworkers observed an efficient reduction of tumorigenesis in animal models and in human melanoma cells when reducing SOX10 expression levels and for this anti-tumoric effect they found SOX9 to be required as a functional antagonistic regulator of SOX10." (PMID 26927636, 2016). "Interestingly, it was reported SOX10 is expressed in melanoma cells, where it is apparently involved in formation and progression of melanoma." (PMID 25352156, 2016). "On the other hand, enforced expression of TAF4 promoted expression of pluripotency- associated KLF4, OCT4 and NANOG, and NC-related MSX2, PAX7, SOX10 and SNAI1, reaffirming the critical role of hTAF4-TAFH activity in the maintaining of multipotency in melanoma cells." (PMID 27499390, 2016). "If any correlations to clinical findings in melanoma patients could be seen, further studies will be needed to further clarify statistical significance of the SOX10 level variations between melanoma subgroups found in this study." (PMID 27110718, 2016). "The transcription factor SOX10 is important for normal development and function in melanocytes and nerve cells, and it has been demonstrated to promote the development of giant congenital naevi and melanomas." (PMID 27110718, 2016). "Taken together, SOX5, SOX10 and MITF seem to have a crucial clinical impact and our developed linear regression based expression signature of these three genes associated in particular with melanomas with a small Breslow thickness." (PMID 26927636, 2016).